TRMT10A (tRNA methyltransferase 10A)
Description:
S-adenosyl-L-methionine-dependent guanine N(1)- methyltransferase that catalyzes the formation of N(1)-methylguanine at position 9 (m1G9) in tRNAs. Probably not able to catalyze formation of N(1)-methyladenine at position 9 (m1A9) in tRNAs.
Synonyms: RG9MTD2; MGC27034; TRM10; HEL-S-88; MSSGM; MSSGM1
Tractability: Small molecule: a structure with a bound ligand is known.
Gene: Protein-coding gene on chromosome 4 (99,546,709 to 99,564,039, reverse strand). Ensembl gene ENSG00000145331.
Subcellular location: Nucleus; Nucleus, nucleolus
Subcellular location (Human Protein Atlas): Actin filaments; Nucleoli; Nucleoplasm; Cytosol
Pathways (Reactome):
Metabolism of RNA: tRNA modification in the nucleus and cytosol
Gene Ontology:
Molecular function: protein binding; RNA binding; tRNA (guanosine(9)-N1)-methyltransferase activity; tRNA binding; methyltransferase activity
Biological process: tRNA methylation; tRNA N1-guanine methylation
Cellular component: cytosol; extracellular exosome; nucleolus; nucleoplasm; nucleus
Genetic constraint (gnomAD): Loss-of-function variants: 35 observed, 39.29 expected, observed/expected ratio (o/e) 0.89, 90% interval 0.68 to 1.18. The synonymous counts are far from expectation, so gnomAD's model fits this gene poorly and the ratio says little. Missense variants: 383 observed, 416.37 expected, observed/expected ratio (o/e) 0.92, 90% interval 0.85 to 1. Synonymous variants: 101 observed, 137.44 expected, observed/expected ratio (o/e) 0.73, 90% interval 0.62 to 0.87.
Homologues: Orthologues: chimpanzee TRMT10A (99% identical), macaque TRMT10A (96% identical), dog TRMT10A (89% identical), pig TRMT10A (88% identical), guinea pig TRMT10A (80% identical), mouse Trmt10a (75% identical), rat Trmt10a (74% identical), tropical clawed frog trmt10a (59% identical), zebrafish trmt10a (58% identical), Caenorhabditis elegans trmt-10A (27% identical), Drosophila melanogaster CG14618 (27% identical). Paralogues in human: TRMT10B (24% identical), TRMT10C (20% identical).
Diseases named in the same sentence as TRMT10A in open-access papers:
TRMT10A is named in the same sentence as 17 diseases in open-access papers, as found by Europe PMC text mining. Sharing a sentence is not in itself a finding about the gene and the disease. The quoted sentences say what the papers report.
microcephaly (9 papers, 2013 to 2024). A congenital or acquired developmental disorder in which the circumference of the head is smaller than normal for the person's age and sex. "Human patients with homozygotic TRMT10A mutations typically show short stature, diabetes, and brain-related pathologies (microcephaly and intellectual disability)." (PMID 38950903, 2024). "Pathogenic mutations in TRMT10A cause intellectual disability, microcephaly, diabetes, and short stature in humans, and generate cytotoxic tRNA fragments in cultured cells; however, it is not clear how TRMT10A supports codon translation or brain functions." (PMID 38950903, 2024). "TRMT10A is crucial for human health, and homozygotic mutations in the TRMT10A gene is associated with microcephaly, intellectual disability, diabetes, and short stature." (PMID 38950903, 2024). "In humans, mutations in the TRMT10A gene are linked to microcephaly and intellectual disability, as well as defects in glucose metabolism." (PMID 37949221, 2023). "Mutations in mt-tRNA genes are associated with maternally inherited diabetes and deafness (MIDD) and insulin resistance and mutations in the tRNA methyltransferase TRMT10A cause young onset diabetes and microcephaly." (PMID 33419045, 2021). "Homozygous inactivating mutations in the TRMT10A gene cause young onset diabetes, microcephaly, intellectual disability, and epilepsy." (PMID 33419045, 2021). "In conclusion, we describe a nonsense mutation in the TRMT10A gene in a new syndrome of young onset diabetes and microcephaly." (PMID 24204302, 2013). "This is the first study describing the impact of TRMT10A deficiency in mammals, highlighting a role in the pathogenesis of microcephaly and early onset diabetes." (PMID 24204302, 2013). "Polymorphisms or mutations in tRNA methyltransferases, such as in CDKAL1 and TRMT10A, are associated with glucose intolerance due to impaired insulin synthesis and, in the case of TRMT10A, cause a monogenetic form of young-onset diabetes associated with microencephaly and intellectual disability." (PMID 32894308, 2020). "Trm10 is conserved throughout Eukarya and Archaea, and mutations in the human gene (TRMT10A) have been linked to neurological disorders such as microcephaly and intellectual disability, as well as defects in glucose metabolism." (PMID 37949221, 2023). "Individuals with microcephaly, short stature, and impaired glucose metabolism 1 (MIM# 616033) due to TRMT10A variants are known to be at risk for early-onset diabetes, usually by the second decade." (PMID 34276053, 2021). "TRMT10A sequencing should be considered in children or adults with young-onset diabetes who have a history of intellectual disability, microcephaly and epilepsy." (PMID 26526202, 2016). "Here we identified a nonsense mutation in TRMT10A (also called RG9MTD2) in a new syndrome of young onset diabetes and microcephaly." (PMID 24204302, 2013). "We show that TRMT10A is ubiquitously expressed but enriched in brain and pancreatic islets, consistent with the tissues affected in this new syndrome of diabetes and microcephaly." (PMID 24204302, 2013). "In addition to causing microcephaly and short stature, the TRMT10A mutation causes a severe form of diabetes, which was not reported for these other RNA methyltransferase mutations." (PMID 24204302, 2013).
diabetes (8 papers, 2013 to 2024). "Several case reports have highlighted that mutations in TRMT10A can lead to diabetes, autosomal‐recessive intellectual disability (ARID), microcephaly, and short stature." (PMID 38943267, 2024). "We showed that 5′-tRFsGln mediate pancreatic β-cell failure in diabetes caused by inactivating mutations in the tRNA-modifying enzyme TRMT10A." (PMID 33419045, 2021). "In addition to diabetes, the patients also suffered from microcephaly and intellectual disability, and genotype testing suggested homozygous mutations in the TRMT10A gene." (PMID 36923941, 2023). "Recently, several cases have been reported that TRMT10A is associated with childhood diabetes." (PMID 36923941, 2023). "Additionally, Trmt10A deficiency contributes to impaired glucose regulation and the pathogenesis of early onset diabetes by negatively impacting β-cell mass." (PMID 36736767, 2023). "A report suggests higher murine atrial m1G levels indicate a potential tissue‐specific activity of TRMT10A in diabetes." (PMID 38943267, 2024). "This suggests that Trmt10A activity in diabetes may be tissue specific." (PMID 36736767, 2023). "We furthermore sequenced TRMT10A in 26 patients with non-autoimmune diabetes with onset before 25 years and a positive family history of diabetes, in whom no mutation was identified in known MODY-associated genes, but did not identify any mutation in TRMT10A." (PMID 24204302, 2013).
glioma (4 papers, 2023 to 2026). A benign or malignant brain and spinal cord tumor that arises from glial cells (astrocytes, oligodendrocytes, ependymal cells). "Downregulation of TRMT10A expression significantly promotes VM formation in vitro, while upregulation of TRMT10A has the opposite effect, suggesting that abnormal TRMT10A expression is associated with VM formation in gliomas." (PMID 40140670, 2025). "In gliomas, tRNA methyltransferase 10 homologue A (TRMT10A) expression is significantly downregulated in glioma cells, leading to reduced m1G9 modification of tRNA-argcct." (PMID 41550494, 2026). "Our preliminary work demonstrated that downregulating TRMT10A in U251 glioma cells led to the upregulation of differentially expressed tRFs, with tRF-22-8XF6RE98N (tRF-22) showing the most significant increase." (PMID 40140670, 2025). "This study confirmed that downregulation of TRMT10A in glioma cells reduces m1G9 modification of tRNA-ArgCCT, decreasing tRNA stability and upregulating tRF-22." (PMID 40140670, 2025). "They found that knockdown of TRMT10A expression in U251 glioma cells resulted in upregulation of tRNA-Arg-CCT-derived tRF-22 (tRF-22-8XF6RE98N) along with decrease in m1G9 modification of tRNA-Arg-CCT." (PMID 41415912, 2025). "To investigate how TRMT10A promotes VM formation in glioma cells, we knocked down TRMT10A in U-251 MG cells and analyzed the differentially expressed tRFs using Human tRF & tiRNA sequencing." (PMID 40140670, 2025). "Knockdown of TRMT10A reduces m1G9 modification of tRNA-ArgCCT, upregulates tRF-22 expression, and promotes glioma cell proliferation, migration, invasion, and tube formation." (PMID 40140670, 2025). "In this study, TRMT10A expression is downregulated in glioma tissues and cells, correlating with poor prognosis in patients." (PMID 40140670, 2025). "In conclusion, this study demonstrated that the expression of TRMT10A is downregulated in glioma cells, which reduces m1G9 modification of tRNA-ArgCCT, decreases tRNA stability, and upregulates tRF-22 expression." (PMID 40140670, 2025). "CGGA data analysis revealed that TRMT10A expression is significantly downregulated in WHO grade IV primary glioma samples compared to grade II samples, consistent with the protein expression levels." (PMID 40140670, 2025). "This study elucidates the mechanism by which TRMT10A affects VM formation in gliomas and provides a novel therapeutic target for GBM." (PMID 40140670, 2025). "Analysis of CGGA data revealed that TRMT10A expression was significantly lower in WHO grade IV primary glioma samples compared to WHO grade II samples." (PMID 40140670, 2025). "The mRNA and protein levels of TRMT10A were lower in glioma cells (U-87 MG, U-251 MG, T98G) compared to human astrocytes (SVG p12)." (PMID 40140670, 2025). "CGGA data show TRMT10A is significantly downregulated in WHO grade IV gliomas compared to grade II, correlating with poor prognosis." (PMID 40140670, 2025). "The subcutaneous and orthotopic glioma xenograft models in nude mice were used to elucidate the inhibitory effects of the TRMT10A/tRF-22/MXD1 pathway on glioma." (PMID 40140670, 2025). "Upregulated TRMT10A significantly decreased glioma cell viability, migration, invasion, and tube formation compared to OE-NC cells." (PMID 40140670, 2025). "TRMT10A downregulation significantly increased U-251 MG and T98G glioma cell viability, migration, invasion, and tube formation compared to sh-NC cells." (PMID 40140670, 2025). "This study elucidates the mechanism by which TRMT10A affects VM formation in glioma and provides a novel therapeutic target for GBM." (PMID 40140670, 2025). "IHC and FISH staining of glioma tissue revealed that the expression levels of TRMT10A were significantly elevated in the OE-TRMT10A and OE-TRMT10A + sh-tRF-22 groups compared to the OE-NC + sh-NC group." (PMID 40140670, 2025). "The role of TRMT10A in glioma VM formation remains unexplored." (PMID 40140670, 2025).
glioma (continued). "In human glioma cells, TRMT10A expression is significantly lower than in human astrocytes." (PMID 40140670, 2025). "Moreover, overexpression of wild-type tRNA-ArgCCT, but not that of G9 methylation site mutant (G9U), increased tRF-22 expression in glioma cells with TRMT10A knockdown." (PMID 40140670, 2025). "Finally, in vivo experiments demonstrated that the simultaneous overexpression of TRMT10A and inhibition of tRF-22 significantly reduced glioma size and VM numbers more effectively than either TRMT10A overexpression or tRF-22 inhibition alone." (PMID 40140670, 2025). "By analyzing CGGA dataset, the expression of TRMT112 which modifies m2G6 was significantly higher in the GBM group than that in the grade II glioma group, while the expression of TRMT10A which modifies m1G9 in the GBM group was significantly lower than that in the grade II glioma group." (PMID 37864150, 2023). "When the G9 position of tRNA-ArgCCT is mutated, downregulation of TRMT10A expression does not alter the level of tRF-22, suggesting that in glioma cells, downregulated TRMT10A increases tRF-22 expression by reducing the m1G9 modification of tRNA-ArgCCT, thereby decreasing tRNA stability." (PMID 40140670, 2025). "Immunohistochemistry staining revealed that TRMT10A, mainly as cytoplasmic staining was found to be highly expressed in non-neoplastic brain tissues, while no strong immunoreactivity was detected in glioma tissues of low-grade (LGG, WHO I-II) and high-grade (HGG, WHO III-IV)." (PMID 40140670, 2025).
adult onset diabetes (2 papers, 2013 to 2016). "It is possible that TRMT10A haploinsufficiency increases the risk for adult onset diabetes." (PMID 24204302, 2013).
chronic myelogenous leukemia (1 paper, 2020). "Two KO clones for TRMT10A (here abbreviated ΔA4 and ΔA10) and two for TRMT10B (ΔB4 and ΔB9) were generated by a commercial supplier in HAP1 cells, a nearly-haploid human cell line derived from the chronic myelogenous leukemia cell line KBM-7." (PMID 32392304, 2020).
colorectal cancer (1 paper, 2013). A primary or metastatic malignant neoplasm that affects the colon or rectum. "A single study suggested altered TRMT10A mRNA expression in colorectal cancer." (PMID 24204302, 2013).
insulinoma (1 paper, 2020). "It was previously reported that the depletion of TRMT10A causes a slight increase of protein translation in the rat insulinoma cell line INS-1E." (PMID 32392304, 2020).
tumor (2 papers, 2018 to 2025). "Overexpression of TRMT10A and inhibition of tRF-22 significantly reduces xenograft tumor size and VM formation in nude mice." (PMID 40140670, 2025). "Overexpression of TRMT10A combined with tRF-22 inhibition significantly reduces the number of VM channels and inhibits tumor growth in xenograft models in nude mice." (PMID 40140670, 2025).
brain disorder (1 paper, 2024). A disease affecting the brain or part of the brain. "Considering that m6A-modified RNAs accumulate in the synaptic compartment following learning, further studies from the perspective of mRNA m6A modification would deepen our understanding of how TRMT10A deficiency causes brain disorders." (PMID 38950903, 2024).
neurodevelopmental disorder (1 paper, 2020). A behavioral and cognitive disorder with onset during the developmental period that involves impaired or aberrant development of intellectual, motor, or social functions. "In humans, loss-of-function mutations in TRMT10A are associated with a severe neurodevelopmental disorder and early-onset diabetes." (PMID 32392304, 2020).
TRMT10A also shares sentences with these, for which no sentence is quoted: Intellectual disability (4 papers); epilepsy (1); glioblastoma (1); Glucose intolerance (1); influenza (1); neurological disorders (1); Primary microcephaly (1).